IL1R1 (interleukin 1 receptor type 1)
Diseases named in the same sentence as IL1R1 in open-access papers (continued):
Sharing a sentence is not in itself a finding about the gene and the disease.
influenza (11 papers, 2011 to 2025). An acute viral infection of the respiratory tract, occurring in isolated cases, in epidemics, or in pandemics; it is caused by serologically different strains of viruses (influenzaviruses) designated A, B, and C, has a 3-day incubation period, and usually lasts for 3 to 10 days. "While an IL-1R1 deficiency could lessen exaggerated inflammatory responses in smoke-exposed influenza-infected animals, we hypothesized that IL-1α would play a predominate role in promoting this response." (PMID 22163019, 2011). "While it is well understood that an IL-1R1-deficiency increases influenza-related mortality at time-points later than were assessed in this paper, studies are on-going to examine the outcome of IL-1α blockade to antiviral responses (later than 5 days post-infection) in smoke-exposed mice." (PMID 22163019, 2011). "Indeed, IL-1R1 deficiency attenuated exacerbated neutrophilic responses in cigarette smoke-exposed influenza-infected animals." (PMID 22163019, 2011). "Preferential increase in IL-1R1 expression on TFH cells suggests a functional relevance in the GC, but we wanted to confirm that T cell specific IL-1R1 signaling had functional consequences within the GC post influenza infection." (PMID 40825032, 2025). "Using B cell specific ablation of IL-1β production and T cell specific ablation of IL-1R1 signaling post influenza infection, we show that B cell-derived IL-1β is essential for the establishment of TFH cells and therefore GCs." (PMID 40825032, 2025). "Our work confirms the need for IL-1 signaling on TFH cells in influenza infection as we show that TFH cells, post influenza infection, express significantly more IL-1R1 and mice with IL-1R1 deficient T cells display significant reductions in numbers of TFH and GC B cell." (PMID 40825032, 2025). "Considering the limited inhibition of viral replication that occurs through IL-1R1 signaling, it seems that inflammatory injury plays a more important role in influenza-induced acute lung injury than direct viral proliferation effects upon respiratory H1N1 infection." (PMID 28585438, 2017). "While IL-1R1 deficiency did not significantly affect total BAL inflammation in smoke-exposed influenza-infected mice (p = 0.089), neutrophilia was significantly attenuated in these animals compared to wild-type controls." (PMID 22163019, 2011).
pancreatic cancer (11 papers, 2016 to 2025). "↑ uPA, ↑ MMP-1 and ↑ IL1-R1 in human pancreatic tumours. ↑ MMP-1 expression associated with ↑ PDAC tumour stage." (PMID 35204653, 2022). "We found that TGFβ down-regulated the expression of IL-1R1 on the stellate cells, which resulted in inhibition of the responses to IL-1α, with loss of the stimulatory effect of IL-1α on the ability of pancreatic stellate cells to enhance migration of the pancreatic carcinoma cells." (PMID 27473228, 2016). "The age-associated decline of DNMT3A enhances IL-1α production, and disrupting IL-1R1 signaling early during tumor development normalized myelopoiesis and slowed the growth of lung, colonic, and pancreatic tumors." (PMID 39236155, 2024). "Tumor stroma interactions induced by IL-1α/IL-1R1 signaling have been shown to be involved in pancreatic cancer cell migration." (PMID 27473228, 2016). "IL1A/IL-1R1 signaling was involved in pancreatic cancer cell migration." (PMID 36741321, 2023). "Taken together, these results showed that IL1β secreted from pancreatic cancer cells could activate NF-κB signaling in SCs via IL1R1 to promote pro-inflammatory cytokine production." (PMID 32308766, 2020). "Dosch et al36 demonstrated that the human IL-1R1 antagonist anakinra significantly reduced IL-6 levels and inhibited STAT3 activation in pancreatic tumors derived from PKT mice." (PMID 40060615, 2025).
dermatitis (10 papers, 2014 to 2023). An inflammatory process affecting the skin. "Of note, previous studies have demonstrated that IL1β is an essential cytokine for synergistically acting with IL-23 to stimulate IL-1R1+ γδ T cells to producing IL17 in skin inflammation." (PMID 35922852, 2022). "We crossed Il1a−/−, Il1b−/−, and Il1r1−/− mice onto the Flgft/ft background to investigate their contribution to spontaneous skin inflammation." (PMID 30937919, 2019). "IL-1β and TNF are important in this model, since both Il1r1−/− and Tnf−/− mice showed significantly reduced dermatitis." (PMID 27982014, 2016). "Il1r1 deletion significantly delayed the appearance of dermatitis, with markedly reduced epidermal hyperplasia in 13-week-old Shpnm/mIl1r1−/− mice compared with 12-week-old Shpnm/m mice." (PMID 25443632, 2014). "Imiquimod-induced skin inflammation is partially reduced in mice deficient for both IL-1α/IL-1β or for IL-1R1, but not in IL-1α- or IL-1β-deficient mice, demonstrating the redundant activity of IL-1α and IL-1β for skin inflammation." (PMID 31156649, 2019). "IMQ-induced skin inflammation has been shown to demand IL-1R1 signaling." (PMID 31357710, 2019). "More importantly, the expression of IL1B induced hyper-activation of IL-1R1-expressing mast cells, while the treatment of anti-IL1B antibody can reduce the aggravation of dermatitis in spontaneous mice models of AD with a defective skin barrier." (PMID 37330465, 2023).
Stroke (10 papers, 2006 to 2025). Sudden impairment of blood flow to a part of the brain due to occlusion or rupture of an artery to the brain. "In conclusion, brain endothelial and neuronal (cholinergic) IL-1R1 are key contributors to the detrimental actions of IL-1 in the brain after stroke." (PMID 30453020, 2019). "In contrast, deletion of IL-1R1 in IL-1R1fl/fl Δ Nestin mice altered microglial process coverage of neurons, which indicates changes in microglia-neuron interactions after stroke." (PMID 30453020, 2019). "Brain endothelial cells are activated by IL-1 after stroke via binding of IL-1R1, leading to the upregulation of ICAM-1, VCAM-1 and P-Selectin expression, as well as various chemokines, resulting in neutrophil adhesion and infiltration." (PMID 30453020, 2019). "In addition to Il6, we also observed downregulation of Il1a and Il1b in male stroke brains, and downregulation of Il1r1 in female stroke brains upon genetic ablation of MMP-3." (PMID 39000490, 2024). "Cell-specific targeting of IL-1R1 in the brain could therefore have therapeutic benefits in stroke and other cerebrovascular diseases." (PMID 30453020, 2019). "Cell-specific targeting of IL-1R1 in the brain could have major therapeutic benefit in stroke and other cerebrovascular disease by allowing more selective targeting, improving efficacy and reducing any potential side effects." (PMID 30453020, 2019). "Given that IL-17A producing γδ T cells play a crucial role in neutrophil infiltration following stroke and are known to express IL1-R1, we hypothesized that IL-1 also drives neutrophil infiltration into the ischemic hemisphere through the induction of IL-17A in γδ T cells." (PMID 35384588, 2022). "Since our data demonstrate that brain endothelial IL-1R1 contributes to brain damage and BBB dysfunction, we next investigated the possible mechanisms underlying brain endothelial IL-1R1 deletion-induced ischaemic damage, by assessing stroke induced neutrophil infiltration after IL-1R1 deletion." (PMID 30453020, 2019). "We also show that IL-1R1 signalling deletion in platelets or myeloid cells does not contribute to brain injury after experimental stroke." (PMID 30453020, 2019). "This new ubiquitous deletion of IL-1R1 did not significantly influence brain injury after stroke in the present experimental model, similar to what was found previously in other IL-1R1 KO mouse strains." (PMID 30453020, 2019). "In contrast, neuronal IL-1R1 deletion reduced infarct size whilst having no influence on cerebral perfusion changes after stroke." (PMID 30453020, 2019). "We now show in vivo that mice lacking IL-1R1 on brain endothelial cells exhibit reduced cerebrovascular expression of ICAM-1 and VCAM-1 that is accompanied by a marked reduction in the number of neutrophils infiltrating the brain in response to stroke, supporting our previous in vitro findings." (PMID 30453020, 2019).
breast tumor (9 papers, 2016 to 2024). "We recently showed that IL-1R1 antagonist Anakinra reduces the number of microvessels in sub-cutaneous breast tumours and bone metastases caused by the osteotrophic triple-negative breast cancer cell line MDA-MB-231-IV, after both a preventative and treatment strategy." (PMID 29760166, 2018). "To determine the clinical significance of identifying IL1R1 as facilitating AE resistance, we assessed IL1R1 gene expression levels in patient breast tumors." (PMID 32707076, 2020). "However, IL1R1, ILRAP, IL6ST, CXCL3, CXCL5, and CXCL6 gene expression was higher in normal adjacent tissue than in breast tumor tissue." (PMID 39201290, 2024). "However, IL1R1, ILRAP, IL6ST, CXCL3, CXCL5, and CXCL6 gene expression levels were higher in normal adjacent tissue than in breast tumor tissue indicating that the surrounding non-tumor tissue could also present an inflammation." (PMID 39201290, 2024).
lung carcinoma (9 papers, 2014 to 2025). "To date, no other trials are testing blockade of IL-1R1 signaling for lung cancer therapy." (PMID 39236155, 2024).
prostate carcinoma (9 papers, 2005 to 2025). A carcinoma that arises from epithelial cells of the prostate gland. "Therefore, the homeostasis of normal prostate tissues and androgen-sensitive prostate cancers might be established by the driving force of androgen signaling and the inhibitory functions of inflammatory signaling, such as IL1β/IL1R1." (PMID 33322099, 2020). "Implication of the IL1R1 and IL1RN genes directly implicates the gouty inflammation pathway in prostate cancer." (PMID 40385401, 2025). "In addition, the expression of IL1R1, FOXM1 and PC4 changes markedly during the progression of normal prostate to metastasised prostate cancer." (PMID 15642172, 2005).
schizophrenia (9 papers, 2016 to 2025). A major psychotic disorder characterized by abnormalities in the perception or expression of reality. "Variations in IL1R1 expression have been studied with a focus on traumatic and ischemic brain disease models, mood disorders, and schizophrenia." (PMID 32531902, 2020). "Age of onset negatively correlated with CD14, IL6R, IL1R1, SERPINA3, pan-GFAP and VIM mRNAs in schizophrenia and CD14, IL1B, SERPINA3, pan-GFAP and VIM mRNAs in bipolar disorder." (PMID 34911938, 2021). "Therefore, we investigated inflammation in the SEZ by defining those with low and high levels of inflammation using cluster analysis of IL6, IL6R, IL1R1 and SERPINA3 gene expression in 32 controls, 32 schizophrenia and 29 bipolar disorder cases." (PMID 34911938, 2021).
candidiasis (8 papers, 2010 to 2025). Infection with the organism Candida. "Our results suggest that Il1r1-/- mice are highly susceptible to systemic candidiasis, especially in the kidney and brain." (PMID 40097388, 2025). "Similarly, the IL-1 receptor 1 (IL1R1) and IL-1 receptor antagonist (IL1Rn) were poorly induced by Candida infection in WT and inflammasome deficient mice." (PMID 22174673, 2011). "To assess whether IL-1R-signaling in endothelial cells is critical for protection from systemic candidiasis, we generated mice allowing inducible deletion of Il1r1, specifically in endothelial cells." (PMID 40097388, 2025). "We asked whether the hypoxic environment in the kidneys of Il1r1-/- mice during candidiasis can promote fungal hyphae formation." (PMID 40097388, 2025). "Infection of Il1r1 KO/WT criss-cross bone marrow chimeras and vavcreIl1r1fl/fl mice revealed that IL-1R-signaling in non-hematopoietic cells plays the decisive role in protecting against candidiasis." (PMID 40097388, 2025). "IL-1R1 also mediates the host response in pulmonary candidiasis, and we identified a similar role for IL-1R1 and MyD88 in trauma-induced and biofilm-associated Fusarium keratitis, indicating that the cornea employs similar responses to regulate infection by filamentous fungi." (PMID 20617171, 2010). "From these data, we conclude that the defense against systemic candidiasis strongly depends on Il1r1 expression in non-hematopoietic cells, while IL-1R signaling in hematopoietic cells plays a less critical role." (PMID 40097388, 2025). "Candida infection promoted mTOR phospohorylation in WT but not in IL-1R1-/- Tregsin vivo." (PMID 33240286, 2020).
endotoxemia (8 papers, 2010 to 2022). "Taken together, our results from different doses of LPS, plus data from mutant mice, strongly indicate a critical role of the NLRP3-IL1β-IL-1R1 pathway in mediating the transition from acute to chronic neuroinflammation incited by severe endotoxemia." (PMID 32070376, 2020). "Outcome of endotoxemia was unaffected in IL-1α TM mice, consistent with previous findings in Il1r1-/- mice." (PMID 30926232, 2019).
tuberculosis (8 papers, 2012 to 2021). A chronic, recurrent infection caused by the bacterium Mycobacterium tuberculosis. "In a murine model of TB, IL-1α/β double knockout mice or mice deficient in IL-1R1 display increased susceptibility to M. tuberculosis infection." (PMID 29189980, 2018).
Autoimmunity (7 papers, 2014 to 2025). The occurrence of an immune reaction against the organism's own cells or tissues. "While mechanisms leading to inflammation and autoimmunity remain to be elucidated in the Ptp6n-/- mice, the underlying processes are similar to the IL-1R1 dependency of cigarette smoke-induced ANA production and BALT formation." (PMID 24754996, 2014). "One of the main mediators of inflammation is interleukin 1 (IL–1), which, through its IL–1 type 1 receptor (IL–1R1), leads to autoimmunity and the development of a number of autoinflammatory diseases." (PMID 40217938, 2025). "We also found increased expression for the IL1R1 gene, an important regulator in both inflammation and autoimmunity." (PMID 26086874, 2015). "This miRNA cluster is connected to the pathogenicity of Th17 due to pathogenic cytokine production, including IL-17A and IL-17F, and mediates autoimmunity by repression of FOXO1 and induction of IL-1R1 expression." (PMID 37834058, 2023).
endometriosis (7 papers, 2006 to 2025). The growth of functional endometrial tissue in anatomic sites outside the uterine body. "It was reported that the NLRP3 inflammasome was involved in the exacerbation of endometriosis in a mouse model, consistent with our current findings showing smaller lesions in IL-1R1-deficient mice." (PMID 31507610, 2019). "To clarify the role of IL-1 in lesion formation, we used C57BL/6-background IL-1R1-deficient mice for the endometriosis model." (PMID 31507610, 2019). "Strong expression of IL‐1R1 is related to the risk of developing endometriosis." (PMID 26471943, 2015). "There was also a tendency for eutopic endometrium from endometriosis cases to express higher IL1R1 and lower IL1A and IL1B." (PMID 40938538, 2025). "IL1R1 imbalance in ectopic endometrial tissue of women suffering from / with endometriosis results in heightened sensitivity to IL1 stimulation, which affects their ability to develop into host tissues for implantation." (PMID 38745948, 2024). "We investigated the role of IL-33, IL-1R1, and MyD88 in the development of endometriosis in mice, and demonstrated the potential of inhibitors for IL-1/IL-33 and their signaling pathway as therapeutic targets for endometriosis." (PMID 31507610, 2019). "Polymorphisms in IL1R1 gene has been associated with other diseases as well, for instance AIDS progression, endometriosis and Helicobacter pylori infection." (PMID 20353565, 2010). "IL-1R1 was down-regulated in the eutopic endometrium of baboons experimentally induced with endometriosis." (PMID 17118171, 2006). "Therefore, we propose that the reduced levels of endometrial IL-1R1 observed in baboons with endometriosis provide further evidence that this endometrium is incapable of responding to and/or mediating signals generated from the implanting embryo." (PMID 17118171, 2006). "Furthermore, we demonstrated that neutralizing antibodies to IL-33 and/or IL-1R1, or an inhibitor of IRAK4 (involved in MyD88 signaling) were effective for the treatment of endometriosis in this model." (PMID 31507610, 2019). "Reduction of IL-1R1 in the eutopic endometrium of baboons with induced endometriosis may increase the proliferative index of the endometrium; furthermore, aberration of αvβ3 expression seen in women with endometriosis may be mediated by the reduction of IL-1β signaling in the absence of IL-1R1." (PMID 17118171, 2006).
fibrosis (7 papers, 2015 to 2024). the formation of excess fibrous connective tissue in an organ or tissue in a reparative or reactive process. "Our results are unique from the well-established bleomycin model of fibrosis, in which the end results of tissue injury, chronic inflammation, and pulmonary fibrosis induced by bleomycin were attenuated in IL-1R1 deficient mice." (PMID 28903780, 2017). "We demonstrate that deletion of IL-1R1 significantly reduced WBC, neutrophil and platelet counts and ameliorated BM fibrosis in homozygous Jak2V617F (Jak2VF/VF) knock-in mouse model of myelofibrosis." (PMID 36100596, 2022).
gastric cancer (7 papers, 2015 to 2025). A primary or metastatic malignant neoplasm involving the stomach. "IL-1β, a ligand of IL-1R1, is well known as a pro-inflammatory cytokine and its over-expression is an essential risk factor in gastric cancer." (PMID 26870992, 2016). "Besides IL-1and IL-1R1, many other cytokines and associated receptors, for example IL-6 and TNFα, are involved in the progression of gastric cancer and can activate NF-κB signaling." (PMID 26870992, 2016). "Our results reveal NF-κB, HNF4α and IL-1R1 are all part of the self-perpetuating circuit connecting gastritis to gastric cancer." (PMID 26870992, 2016). "We further examined HNF4α and IL-1R1 expression in 90 gastric cancer samples and corresponding normal tissues." (PMID 26870992, 2016). "Survival curves were plotted to compare patient outcomes in different expression levels of HNF4α and IL-1R1 and we found a reduction of survival time in patients with high co-expression levels of HNF4α and IL-1R1 in different types of gastric cancer." (PMID 26870992, 2016). "HNF4α and IL-1R1 showed an increasing trend along with the severity of atrophic gastritis already, which was in accordance with the results in mice, and were increased in gastric cancer samples." (PMID 26870992, 2016). "Since cell surface receptors control communication with the outside environment and can modify important cellular functions, we compared expression of 21 cell surface receptors between atrophic gastritis and gastric cancer, and identified IL-1R1 as most significantly increased in GC." (PMID 26870992, 2016).
ischemic stroke (7 papers, 2018 to 2025). A stroke disorder caused by obstruction of blood flow to the brain, due to thrombotic (local blood clot formation) or embolic (due to a blood clot or other material traveling from another site) event. "Brain endothelial and neuronal (cholinergic) IL-1R1 has also been shown to mediate the detrimental effects of IL-1 in the brain during an ischemic stroke." (PMID 35432334, 2022). "Interestingly, in acute MI and ischemic stroke, the expression of APAF1 and IRAK3 was negatively correlated with the abundance of NK cells, while the expression of ATM, CAPN1, IL1B, IL1R1, PRKACA, PRKACB and TNFRSF1A was positively correlated with the abundance of NK cells in MI." (PMID 38526027, 2024). "Interestingly, APAF1 and IRAK3 expression correlated negatively with NK cell abundance in both acute myocardial infarction and ischemic stroke, whereas ATM, CAPN1, IL1B, IL1R1, PRKACA, PRKACB, and TNFRSF1A correlated negatively with NK cell abundance in acute myocardial infarction." (PMID 35432334, 2022).